LIPT2 (lipoyl(octanoyl) transferase 2)
Description:
Catalyzes the transfer of endogenously produced octanoic acid from octanoyl-acyl-carrier-protein (octanoyl-ACP) onto the lipoyl domains of lipoate-dependent enzymes such as the protein H of the glycine cleavage system (GCSH). Lipoyl-ACP can also act as a substrate although octanoyl-ACP is likely to be the physiological substrate (By similarity).
Tractability: No criterion of Open Targets' tractability assessment is met for any kind of drug.
Gene: Protein-coding gene on chromosome 11 (74,490,519 to 74,493,724, reverse strand). Ensembl gene ENSG00000175536.
Subcellular location: Mitochondrion
Pathways (Reactome):
Metabolism of proteins: Protein lipoylation
Gene Ontology:
Molecular function: lipoyl(octanoyl) transferase activity
Biological process: protein lipoylation
Cellular component: mitochondrion; mitochondrial matrix
Genetic constraint (gnomAD): Loss-of-function variants: 16 observed, 9.46 expected, observed/expected ratio (o/e) 1.69, 90% interval 1.09 to 1.95. That is too few expected variants to judge how well the gene tolerates losing a copy. Missense variants: 424 observed, 282.46 expected, observed/expected ratio (o/e) 1.5, 90% interval 1.39 to 1.63. Synonymous variants: 199 observed, 125.68 expected, observed/expected ratio (o/e) 1.58, 90% interval 1.41 to 1.78.
Gene-disease validity (ClinGen):
ClinGen rates the evidence that LIPT2 causes each of these diseases.
mitochondrial disease (autosomal recessive): Limited.
Homologues: Orthologues: chimpanzee LIPT2 (99% identical), macaque LIPT2 (97% identical), dog LIPT2 (88% identical), pig LIPT2 (87% identical), guinea pig LIPT2 (86% identical), mouse Lipt2 (84% identical), rat Lipt2 (83% identical), tropical clawed frog lipt2 (55% identical), zebrafish lipt2 (48% identical), Drosophila melanogaster Lipt2 (45% identical), Caenorhabditis elegans lpl-1 (37% identical).
Diseases named in the same sentence as LIPT2 in open-access papers:
LIPT2 is named in the same sentence as 39 diseases in open-access papers, as found by Europe PMC text mining. Sharing a sentence is not in itself a finding about the gene and the disease. The quoted sentences say what the papers report.
cardiomyopathy (2 papers, 2020 to 2021). A disease of the heart muscle or myocardium proper. "Recessive variants in LIPT1 and LIPT2 can induce a variety of clinical range of disorders from Leigh syndrome to non-ketotic hyperglycemia, hypotonia, seizures, microcephaly, psychomotor retardation, and cardiomyopathy." (PMID 33426505, 2020).
glioma (2 papers, 2023 to 2025). A benign or malignant brain and spinal cord tumor that arises from glial cells (astrocytes, oligodendrocytes, ependymal cells). "Previously, LIPT2 expression has been associated with bad prognosis in glioma, and GLS is recognized as a factor associated with malignant proliferation and invasion in gliomas." (PMID 39913607, 2025). "Thus, the prior identification of AC005229.4, LIPT2 and GLS as having a role in the advancement of gliomas and other types of cancer provides support for our findings." (PMID 39913607, 2025).
Adrenocortical carcinoma (1 paper, 2023). "Upregulation of LIPT2 was significantly associated with shorter PFI in GBMLGG and Adrenocortical carcinoma (ACC), and longer PFI in KIRC, THCA, and CHOL." (PMID 38129565, 2023).
cholangiocarcinoma (1 paper, 2023). A carcinoma that arises from the intrahepatic biliary tree (intrahepatic cholangiocarcinoma) or from the junction, or adjacent to the junction, of the right and left hepatic ducts (hilar cholangiocarcinoma). "In GBM, GBMLGG, LGG, and Pheochromocytoma and Paraganglioma (PCPG), high expression of LIPT2 indicated poor DSS, while low expression of LIPT2 indicated poor DSS in KIPAN, KIRC, Kidney renal papillary cell carcinoma (KIRP), Cholangiocarcinoma (CHOL), and OV." (PMID 38129565, 2023).
Esophageal carcinoma (1 paper, 2023). A primary or metastatic malignant neoplasm involving the esophagus. "We noticed an inverse correlation between LIPT2 expression and TMB in BRCA, Stomach and Esophageal carcinoma (STES), STAD, THYM, CHOL, and DLBC, and an inverse correlation between LIPT2 expression and MSI in GBMLGG, STES, STAD, THYM, and THCA, while a positive correlation was found in UVM." (PMID 38129565, 2023).
liver cancer (1 paper, 2024). An epithelial or non-epithelial malignant neoplasm that arises from the liver. "In light of this background, it is pertinent to inquire, through bioinformatics and subsequent basic experimental validation, we have learned that in numerous cancer types, including liver cancer, LIPT2, LIPT1, and LIAS, which act as precursors for ALA synthesis, exhibit oncogenic activity." (PMID 39199143, 2024).
lung adenocarcinoma (1 paper, 2023). A carcinoma that arises from the lung and is characterized by the presence of malignant glandular epithelial cells. "The results showed that total LIPT2 protein was significantly down regulated in GBM, KIRC, Lung adenocarcinoma (LUAD), and LIHC." (PMID 38129565, 2023).
neonatal encephalopathy (1 paper, 2025). "Patients with LIPT2 mutations have been found to present with severe neonatal encephalopathy, decreased PDH and α-KGDH activity, abnormal leucine metabolism, and reduced protein lipoylation in LIPT2-mutated fibroblasts." (PMID 40897695, 2025).
retinoblastoma (1 paper, 2023). A malignant tumor that originates in the nuclear layer of the retina. "The findings revealed that LIPT2 expression was in a positive correlation with angiogenesis, differentiation, and inflammation in retinoblastoma (RB), and negatively correlated with DNA damage, DNA repair, and cell cycle." (PMID 38129565, 2023).
thymoma (1 paper, 2023). A neoplasm arising from the epithelial cells of the thymus. "Additionally, In ESCA and THCA, LIPT2 expression displayed a positive correlation with endothelial cell infiltration, whereas in PCPG, BRCA, GBM, and thymoma (THYM), it showed an inverse correlation with endothelial cell infiltration." (PMID 38129565, 2023).
Thyroid carcinoma (1 paper, 2023). "In addition, we found through the GEPIA2 website that LIPT2 expression had an impact on the pathological staging of KIRC, Thyroid carcinoma (THCA), and Liver hepatocellular carcinoma (LIHC) patients." (PMID 38129565, 2023).
triple-negative breast carcinoma (1 paper, 2023). An invasive breast carcinoma which is negative for expression of estrogen receptor (ER), progesterone receptor (PR), and human epidermal growth factor receptor 2 (HER2). "In triple-negative breast cancer patients, the overexpression of LIPT2 is related to mutations, and high amplification of LIPT2 is associated with reduced immune infiltration." (PMID 38129565, 2023).
uveal melanoma (1 paper, 2023). A melanoma derived from melanocytes of the uveal tract. "Additionally, the expression of LIPT2 was negatively correlated with cell apoptosis, DNA damage, DNA repair, invasion, and metastasis in uveal melanoma (UM)." (PMID 38129565, 2023).
tumor (11 papers, 2022 to 2024). "Using the GEPIA2 tool in combination with TCGA tumor expression data, we identified the top 100 genes associated with LIPT2 expression." (PMID 38129565, 2023). "Based on the pan-cancer expression profiles from the TGCA, GTEx, and TARGET databases, LIPT2 showed significantly high expression in 26 tumor tissues, including GBMLGG, compared to normal human tissues." (PMID 38129565, 2023). "Tumor purity is known to affect the efficiency of immune checkpoint inhibitor therapy, and we found a significant positive correlation between LIPT2 expression and tumor purity in 17 types of tumors, particularly in KICH and LUSC." (PMID 38129565, 2023). "Single-cell sequencing results revealed the correlation of LIPT2 expression with various biological characteristics such as DNA lesion, tumor angiogenesis, cell apoptosis, metastasis, and invasion." (PMID 38129565, 2023). "In the tumor cell region, the patients with higher expression of LIPT2 and ATP7A had the better prognosis; while the higher the expression of SLC31A1, the worse the prognosis of NPC patients." (PMID 36618352, 2022). "In tumor cell-enriched region, higher expression of SLC31A1 (P = 0.001) was associated with worse prognosis of NPC patients, while the opposite was true for LIPT2 (P = 0.012) and ATP7A (P = 0.011)." (PMID 36618352, 2022). "Since tumor mutational burden (TMB) and microsatellite instability (MSI) are key factors in predicting the efficacy of immunotherapy, we assessed the correlation between LIPT2 expression and pan-cancer TMB and MSI." (PMID 38129565, 2023). "Therefore, we believe that LIPT2 can serve as a tumor immune-related biomarker with potential clinical value in cancer treatment." (PMID 38129565, 2023). "Collectively, these results reveal that deacetylation of SERBP1 at K68 prevents its binding to Lipt2 mRNA, which induces its instability, leading to lower levels of its mRNA and protein in KMM cells and KS tumor cells." (PMID 38470932, 2024). "The results show a significant increase in the expression of SLC3A3, MITD1, LIPT2, ATOX1, PDHB, and GLS in tumor tissues compared to normal esophageal tissues." (PMID 38159255, 2023). "Gene expression profiling showed that SLC31A1, LIPT2, CDKN2A, and GCSH expression was increased in tumor tissues, while NFE2L2, NLRP3, ATP7A, DLD, MTF1, and DLST expression was decreased in tumor tissues compared with normal tissues." (PMID 37065485, 2023). "Specifically, the expression levels of SLC6A3, MITD1, and PDHA1 exhibited an increasing trend with tumor pathological stage, whereas CCS, LIPT2, PDHB, and PDHA1 displayed a decreasing trend in response to radiation therapy." (PMID 38159255, 2023). "Out of the identified regulators, six genes (SLC6A3, MITD1, CCS, LIPT2, ATOX1, and GLS) showed increased expression in tumor tissues, while PDHB had higher expression in normal tissues." (PMID 38159255, 2023). "LIPT2 expression was significantly correlated with progression-free interval (PFI) in five types of tumors and disease-free interval (DFI) in one type of tumor." (PMID 38129565, 2023). "The other five CRGs, including FDX1, SLC31A1, LIPT2, PDHA1 and GCSH, did not have any mutations in tumor samples." (PMID 36479114, 2022). "In tumor cell-enriched region, the expression of COPS5, DLAT, DLD, FDX1, NFE2L2, PDHA1 and PDHB in the high score group is higher than that in the low score group, while the opposite is true for DLST, GCSH and LIPT2 (P <0.05)." (PMID 36618352, 2022).
cancer (7 papers, 2020 to 2025). A tumor composed of atypical neoplastic, often pleomorphic cells that invade other tissues. "This deacetylation inhibits the stabilizing effect of SERBP1 on Lipid acyltransferase 2 (Lipt2) mRNA, subsequently causing Lipt2 degradation and inhibiting ferroptosis, thereby creating a favorable environment for cancer cell formation." (PMID 40302035, 2025). "In the TIMER2 database, the association between LIPT2 expression and immune cell infiltration in cancer was evaluated using various algorithms (TIMER14, EPIC15, QUANTISEQ16, XCELL17, MCPCOUNTER18, CIBERSORT19, and CIBERSORT-ABS)." (PMID 38129565, 2023). "In this research, we identified that LIPT2 expression is strongly linked to the infiltration of diverse immune cells in cancer, including CAFs, B cells, Tregs, monocytes, macrophages, neutrophils, CD8+ T cells, dendritic cells (DCs), and endothelial cells." (PMID 38129565, 2023). "We assessed the mutations of LIPT2 in pan-cancer using the cBioPortal database." (PMID 38129565, 2023). "Furthermore, we assessed the mutation status, methylation levels, and immune status of LIPT2 in pan-cancer." (PMID 38129565, 2023). "Moreover, we resolved the association of LIPT2 expression in pan-cancer to 44 marker genes for three RNA methylation modifications (m1A, m5C, m6A)." (PMID 38129565, 2023). "The expression levels of LIPT2 mRNA in healthy human tissues and cancer cell lines were also studied using the HPA database." (PMID 38129565, 2023). "In almost all cancers, MMR gene mutations were significantly positively correlated with LIPT2 expression." (PMID 38129565, 2023). "In this analysis, we comprehensively evaluated the value of the cuproptosis-related gene LIPT2 in pan-cancer through multiple bioinformatics platforms." (PMID 38129565, 2023). "Functional enrichment analysis reveals the potential molecular pathways of LIPT2 in cancer initiation and progression." (PMID 38129565, 2023). "To further investigate the possible molecular mechanisms of LIPT2 in cancer occurrence and development, we performed enrichment analysis on proteins interacting with LIPT2 and LIPT2-related genes." (PMID 38129565, 2023). "In conclusion, our research reveals a detailed key role of LIPT2 in the progression, prognosis, and immune efficacy of various forms of cancer." (PMID 38129565, 2023). "For this analysis, we evaluated the expression levels and the significance of prognosis of LIPT2 gene in all cancers by various bioinformatics methods." (PMID 38129565, 2023). "The findings illustrated that LIPT2 was strongly expressed in cancers that responded to any anti PD-L1 therapy, with an AUC value of 0.577 for 5-year recurrence-free survival (RFS)." (PMID 38129565, 2023). "This article explores the possible mechanisms and biological roles of LIPT2 in cancer using various bioinformatics techniques." (PMID 38129565, 2023). "The results of the analysis demonstrate the biological significance of LIPT2 in pan-cancer and its good predictive role in immunotherapy response." (PMID 38129565, 2023). "We compared the methylation levels of LIPT2 between pan-cancer tissues and paired normal tissues using UALCAN." (PMID 38129565, 2023). "The results of this study suggest that LIPT2 has a good predictive effect on the response to cancer immunotherapy." (PMID 38129565, 2023). "Next, we further evaluated the relationship between LIPT2 expression and cancer immune infiltration using the EstimateScore, ImmuneScore, and StromalScore." (PMID 38129565, 2023). "The analysis revealed that LIPT2 amplification was found in more than 7 types of cancers, with Bladder Urothelial Carcinoma (BLCA) having the highest LIPT2 amplification rate (> 15%)." (PMID 38129565, 2023). "The outcomes showed that in the majority of cancer cases, LIPT2 expression was eminently positively correlated with MKI67, PCNA, BCL2, BAX, and EPCAM, while showing a significant negative correlation with VIM." (PMID 38129565, 2023).
cancer (continued). "The results demonstrated that LIPT2 expression was negatively correlated with ImmuneScore, EstimateScore and StromalScore in most cancers." (PMID 38129565, 2023). "In summary, our study systematically analyzed the expression differences, prognosis, methylation, genetic alterations, immune regulation, and immune therapy of the cuproptosis-related gene LIPT2 in pan-cancer utilizing diverse bioinformatics techniques." (PMID 38129565, 2023). "We analyzed the impact of LIPT2 expression differences on the prognosis of cancer patients." (PMID 38129565, 2023). "However, there is currently insufficient research on the potential role of LIPT2 in different types of cancer." (PMID 38129565, 2023). "First, we investigated the expression abundance of LIPT2 in pan-cancer in the TCGA dataset." (PMID 38129565, 2023). "We resolved the connection between LIPT2 and 14 functional states of diverse cancers." (PMID 38129565, 2023). "It was found that LIPT2 expression in almost all pan-cancer samples was significantly positively pertinent to the expression of MMR genes, indicating that LIPT2 may promote cancer cell growth through positive regulation of MMR gene expression." (PMID 38129565, 2023). "However, the biological function of LIPT2 in various cancer types and its potential significance in prognosis continue to be unresolved." (PMID 38129565, 2023). "Furthermore, we investigated the impact of LIPT2 expression levels on cancer cell proliferation, apoptosis, and epithelial-mesenchymal transition (EMT)." (PMID 38129565, 2023). "Additionally, we assessed the predictive effect of LIPT2 on cancer immunotherapy response using the ROC Plotter database." (PMID 38129565, 2023). "The results found that LIPT2 was dramatically overexpressed in the vast majority of cancers." (PMID 38129565, 2023). "The findings imply that LIPT2 may be a latent prognostic indicator for various cancers, particularly GBMLGG." (PMID 38129565, 2023). "Single-cell sequencing results suggest that LIPT2 may regulate multiple biological actions of cancer, such as DNA damage repair, angiogenesis, cell cycle, cell apoptosis, invasion, and metastasis." (PMID 38129565, 2023). "This indicates that LIPT2 expression levels may regulate the biological behavior of cancer cells." (PMID 38129565, 2023). "Furthermore, the expression level of LIPT2 influences the prognosis of cancer patients." (PMID 38129565, 2023). "In contrast, eight regulators (PDHA1, ATP7A, LIPT1, LIPT2, GLS, ATP7B, GCSH, and CDKN2A) were upregulated in cancer tissues." (PMID 36672336, 2023). "LIPT2 mRNA was expressed at relatively high levels in most cancer cell lines, and at low levels in normal human tissues, except in the testis, skeletal muscle, and tongue." (PMID 38129565, 2023). "We also evaluated the correlation between the expression of LIPT2 and MMR genes in pan-cancer." (PMID 38129565, 2023). "Germline mutations in LIAS, LIPT2 and LIPT1 result in impaired PDHc and OGDHc activity, but ABHD11 loss did not significantly alter DLAT lipoylation in several cancer lines." (PMID 32792488, 2020).
mitochondrial disease (2 papers, 2020 to 2022). "Some studies have shown that three human mitochondrial diseases that directly affect lipoic acid metabolism result from heterozygous missense and nonsense mutations in LIAS, LIPT1, and LIPT2 genes." (PMID 35619696, 2022). "Three human mitochondrial diseases that directly affect lipoic acid metabolism result from heterozygous missense and nonsense mutations in the LIAS, LIPT1, and LIPT2 genes." (PMID 32508887, 2020).
neurological disorders (1 paper, 2022). "Mammalian LipT2, an octanoyltransferase is associated with vast number of neurological disorders." (PMID 35764173, 2022).
LIPT2 also shares sentences with these, for which no sentence is quoted: breast carcinoma (2 papers); bladder cancer (1); Breast invasive carcinoma (1); colon adenocarcinoma (1); convulsion (1); diffuse large B-cell lymphoma (1); Encephalopathy (1); Glioblastoma multiforme (1); head and neck squamous cell carcinoma (1); Hyperglycemia (1); Leigh syndrome (1); Lung squamous cell carcinoma (1); lymphoid neoplasm (1); ovarian serous cystadenocarcinoma (1); pancreatic adenocarcinoma (1); Pheochromocytoma and Paraganglioma (1); psoriasis (1); sarcoma (1); Stomach (1); Stomach adenocarcinoma (1); testicular germ cell tumor (1); Wilms tumor (1).